ALOXE3 (arachidonate epidermal lipoxygenase 3)
Diseases named in the same sentence as ALOXE3 in open-access papers (continued):
Sharing a sentence is not in itself a finding about the gene and the disease.
Hepatic steatosis (1 paper, 2018). Steatosis is a term used to denote lipid accumulation within hepatocytes. "In vivo, hepatic Aloxe3 expression enhanced insulin sensitivity, attenuated weight gain, and reduced hepatic steatosis in both diet- and genetically induced steatosis models." (PMID 30135298, 2018). "Hepatocyte-specific Aloxe3 expression reduced weight gain and hepatic steatosis in diet-induced and genetically obese (db/db) mouse models." (PMID 30135298, 2018). "It should be noted that genetic disruption of both 12-LOX and 15-LOX in multiple diabetic models largely recapitulates the Aloxe3-mediated enhancement of hepatic insulin sensitivity and reduced hepatic steatosis." (PMID 30135298, 2018).
Hyperinsulinemia (1 paper, 2018). An increased concentration of insulin in the blood. "In contrast, HTFC-fed mice overexpressing hepatic Aloxe3 were protected from HTFC-induced hyperinsulinemia and insulin resistance." (PMID 30135298, 2018).
Hyperkeratosis (1 paper, 2021). Hyperkeratosis is a histopathological term defining a thickened stratum corneum and may be present in many different skin conditions, with many possible overlaps. "However, upregulated FLG reflects hyperkeratosis, while ALOX12B, ALOXE3, and KRT16 are wound-activated genes in the oral mucosa, suggesting an ongoing wound repair process." (PMID 34506598, 2021).
Insulin resistance (1 paper, 2018). Increased resistance towards insulin, that is, diminished effectiveness of insulin in reducing blood glucose levels. "In summary, we identified the lipoxygenase Aloxe3 as a potentially novel effector of the hepatic fasting response that is sufficient to augment basal caloric expenditure, and ameliorate insulin resistance, weight gain, and hepatosteatosis." (PMID 30135298, 2018). "Aloxe3 expression, moreover, enhanced basal thermogenesis and abrogated insulin resistance in db/db diabetic mice." (PMID 30135298, 2018). "Taken together, Aloxe3 is a fasting-responsive hepatocyte effector that is sufficient to attenuate insulin resistance, weight gain, and hepatic fat deposition in dietary and genetically obese models, in part by activating hepatic PPARγ." (PMID 30135298, 2018).
leishmaniasis (1 paper, 2023). Infectious disease that is transmitted through the bite of hematophagous female phlebotomine sand flies. "Thus, both Arhgap44 and Aloxe3 have the potential to modify susceptibility to leishmaniasis, but none of them exhibited differential expression in the skin or spleen." (PMID 37600780, 2023).
lymph node metastasis (1 paper, 2022). "The positive rate of ALOXE3 expression in tumor samples with positive lymph node metastasis (78.3%) was significantly higher than that in those without lymph node metastasis (60.3%) (P < 0.05)." (PMID 35265525, 2022).
prostate carcinoma (1 paper, 2019). A carcinoma that arises from epithelial cells of the prostate gland. "DNA methylation at cg25365794 (ALOXE3) was inversely associated with lung and prostate cancer incidence." (PMID 30678711, 2019). "DNA methylation at cg25365794 (ALOXE3 gene) was inversely associated with lung and prostate cancer." (PMID 30678711, 2019). "Furthermore, an inverse association of cg25365794 (ALOXE3 gene) with prostate cancer was observed (HR (95% CI) per 1 SD increase: 0.78 (0.60, 1.03)), but only the comparison of the middle and the bottom tertile was statistically significant (HR (95% CI) 0.47 (0.24, 0.92))." (PMID 30678711, 2019). "Taken together, the observed associations of DNA methylation at the ALOXE3 gene and lung and prostate cancer development might not be causal." (PMID 30678711, 2019).
tumor (12 papers, 2019 to 2025). "Downregulation of eLOX3/ALOXE3 expression in GBM tumor is associated with increased expression of miR-18a, which downregulates eLOX3/ALOXE3 expression." (PMID 36765904, 2023). "ALOXE3 is an encoding arachidonic acid, whose metabolism plays an important role in tumor progression and metastasis." (PMID 35265525, 2022). "The difference of ALOXE3 positive expression rate between tumor tissues and normal tissues was statistically significant(χ2=21.044, P=0.000)." (PMID 35265525, 2022). "Immunohistochemical results showed that the positive rate of ALOXE3 in RCC tumor tissues (78.1%) was higher than that in LCC tumor tissues (53.6%) (P < 0.05)." (PMID 35265525, 2022). "Western blotting results showed that NOS2 and ALOXE3 expression was significantly increased in tumor tissues compared with that in normal tissues (P < 0.01)." (PMID 35265525, 2022). "Knockdown of ALOXE3 in GBM cells fostered the orthotopic tumor growth and shortened lifespan in mice." (PMID 33579899, 2021). "Altogether, miR-18a/ALOXE3 axis exerts tumor promoting functions by regulating ferroptosis and migration of GBM cells." (PMID 33579899, 2021). "As confirmed by immunohistochemical analysis, levels of YAP in nucleus and ALOXE3 in cytoplasm were greatly increased in tumor tissues generated by YAPS127A mutant LM3 cells." (PMID 34977009, 2021). "The differential expression of NOS2 and ALOXE3 in tumor tissues and normal tissues suggests that NOS2 and ALOXE3 may be involved in the regulation of tumorigenesis and progression." (PMID 35265525, 2022). "The difference of NOS2 positive expression rate between tumor tissues and normal tissues was statistically significant(χ2=17.261, P=0.000).ALOXE3 was positively expressed in 103 cases, with a positive expression rate of 72.5% (103/142), mainly showing moderate and strong positive expression." (PMID 35265525, 2022). "Knockdown of ALOXE3 in GBM cells promotes orthotopic tumor growth in mice." (PMID 33579899, 2021). "Our study reveals that the role of ALOXE3 as a tumor suppressor can trigger ferroptosis and the TRIB3-β-catenin-TCF4 trimeric complex decreased ferroptosis by inhibiting the function of ALOXE3." (PMID 38429254, 2024). "The lipid mediators produced by eLOX3/ALOXE3, including 12-oxo-ETE, have anti-tumor effects, particularly 12-oxo-ETE, which is a ligand for PPARγ." (PMID 36765904, 2023). "Among nuclear YAP negative tumors samples, 53.13% tumor samples exhibited negative staining of ALOXE3." (PMID 34977009, 2021). "In this study, by using models of monolayer cell culture, 3-dimensional (3D) tumor spheroid and tumor xenograft, we demonstrate that YAP is able to promote ferroptosis and lipid peroxides accumulation by transcriptionally upregulating the lipoxygenase ALOXE3." (PMID 34977009, 2021).
cancer (11 papers, 2017 to 2025). A tumor composed of atypical neoplastic, often pleomorphic cells that invade other tissues. "Simultaneously, we were curious about the association between the level of ALOXE3 and prognosis in each cancer." (PMID 38429254, 2024). "Western blotting results showed that NOS2 and ALOXE3 were significantly highly expressed in cancer, and the difference was statistically significant (P < 0.05)." (PMID 35265525, 2022). "In this study, we focused on the regulatory role of ALOXE3 in GBM development mainly due to the role of ALOXE3 in cancer development is yet to be defined." (PMID 33579899, 2021). "Based on publicly available ENCODE TEAD4 ChIP-seq datasets (GSM1614035, GSM1010860, GSM1010868, GSM1010772 and GSM1010875), we found that ALOXE3 is a putative YAP-TEAD4 gene target in various cancer cell lines." (PMID 34977009, 2021). "Although the role of ALOXE3 in cancer development is yet to be defined, growing evidences revealed that the other LOXs members and their oxylipin products are key mediators for tumorigenesis in different types of cancers via diverse mechanisms." (PMID 33579899, 2021). "Other genes, such as ALOXE3, HBQ1, KREMEN2, SYT13, DOK7, CDC5L, and FBXO6, have been reported in several cancers." (PMID 28404969, 2017). "The fact that eLOX3/ALOXE3 is anticancer in nature suggests that a lipid mediator not formed by eLOX3/ALOXE3 is responsible for the pro-cancer properties of 12-LOX." (PMID 36765904, 2023). "The silencing of lipoxygenase (ALOXE3) and and inhibitor of peroxidase (LRRK2) may contribute to elevated pro-cancer COX-mediated peroxidase activity." (PMID 30253781, 2018). "Genes located above TRIM46 in the heatmap, such as ALOXE3, NR4A3, and TMEM88, did not exhibit similar upregulation in advanced-stage cancer tissues." (PMID 39937005, 2025).
metabolic disease (1 paper, 2018). A congenital disorder (due to inherited enzyme abnormality) or acquired (due to failure of a metabolically important organ) disorder resulting from an abnormal metabolic process. "Aloxe3 is, thus, a novel therapeutic mechanism downstream of the fasting response, which can be leveraged against metabolic disease." (PMID 30135298, 2018). "Aloxe3 is, therefore, a potentially novel effector of the hepatocellular fasting response that leverages both PPARγ-mediated and pleiotropic effects to augment hepatic and whole-host metabolism, and it is, thus, a promising target to ameliorate metabolic disease." (PMID 30135298, 2018).
ALOXE3 also shares sentences with these, for which no sentence is quoted: neurological disorders (2 papers); astrocytoma (1); COVID-19 (1); genodermatosis (1); Granuloma (1); hypotrichosis (1); ichthyosis vulgaris (1); keratoderma (1); lymphoma (1); non-small cell lung carcinoma (1); Obesity (1); peeling skin syndrome (1); pustular psoriasis (1); steatosis (1); uterine corpus endometrial carcinoma (1); Vertigo (1).